USH1C (USH1 protein network component harmonin)
Diseases named in the same sentence as USH1C in open-access papers:
USH1C is named in the same sentence as 32 diseases in open-access papers, as found by Europe PMC text mining. Sharing a sentence is not in itself a finding about the gene and the disease. The quoted sentences say what the papers report.
Usher syndrome (46 papers, 2007 to 2025). A syndromic diseae characterized by the association of sensorineural deafness (usually congenital) with retinitis pigmentosa and progressive vision loss. "Usher syndrome type 1C (USH1C) is a genetic disorder caused by mutations in the USH1C gene, which encodes harmonin, a key component of the mechanoelectrical transduction complex in auditory and vestibular hair cells." (PMID 39871419, 2025). "The AAV2/Anc80L65 gene replacement therapy can potentially be adapted for conditions such as Usher syndrome, which is caused by mutations in genes like USH1C, leading to hearing loss, vestibular dysfunction, and retinitis pigmentosa." (PMID 39871419, 2025). "Functionally, gene USH1C encodes a scaffold protein that functions in the assembly of Usher protein complexes and mutation of USH1C is known to be involved Usher syndrome type 1C and sensorineural deafness." (PMID 38827440, 2024). "A four-year-old boy in Family 19 carried a compound heterozygous mutation of USH1C; mutation of this gene can cause Usher syndrome-type 1C characterized as severe hearing impairment and retinitis pigmentosa." (PMID 33781268, 2021). "Adeno-associated virus 2 (AAV2) harboring a Ush1c transgene also restores auditory and vestibular function in a mouse model of Usher syndrome These studies demonstrate the potential of transgene therapy for restoring hearing in cases of genetic hearing loss." (PMID 30274337, 2018). "One form of Usher syndrome results from mutations in USH1C, which encodes Harmonin, a scaffolding protein that localizes to auditory hair cells and is essential for normal hair bundle morphogenesis and mechanotransduction." (PMID 29027038, 2018). "Mutations in Ush1C are associated with Usher syndrome type 1C in humans, and mouse mutants exhibit splayed stereocilia bundles and progressive loss of hair cells and spiral ganglion neurons." (PMID 29073148, 2017). "In a model of human Usher syndrome type 1C (USH1C) treatment with PTC124 was able to rescue translational read-through of a patient mutation in the USH1C gene and restored the functional properties of the protein." (PMID 25292197, 2015). "Variants in USH1C are phenotypically related to Usher syndrome type 1C and DFNB18A." (PMID 40094841, 2025). "From a clinical point of view, three patients have clinical findings suggestive of deafness, which has been previously reported in the literature, where deletions in the ABCC8 gene also cause deletions in an adjacent gene USH1C associated with hearing loss (Usher syndrome)." (PMID 25871929, 2015). "Mutations in USH1C were previously reported to cause the following phenotypes: Usher syndrome type 1 (characterized by congenital profound SNHL, vestibular dysfunction, and RP), nonsyndromic profound SNHL at the DFNB18 locus, and sector RP with early-onset SNHL." (PMID 23251578, 2012). "It is noteworthy that the association of some top-ranked genes to syndromic deafness forms does not exclude them from being good NSHL candidates, as clearly demonstrated by USH1C involved both in Usher syndrome type 1C, and NSHL, depending on which mutations it undergoes." (PMID 20927407, 2010). "SNP array analysis of all 8 individuals in the solved cohort with a deletion of ABCC8 exons 1-22, demonstrated the deletion extended over exons 1-19 of the adjacent USH1C gene, confirming a diagnosis of Usher syndrome type 1c." (PMID 40041288, 2025). "One functional study has demonstrated that mutations in MYO7A weakens its ability to form MYO7A/USH1C/USH1G complex which impairs phase separation, resulting in an abnormal tip-link densities and causing hearing and vision loss in Usher syndrome patients." (PMID 37985665, 2023). "CHI in this condition is similar in its clinical presentation and pathophysiology to the ABCC8-deficient autosomal recessive diffuse form, while the remainder of the phenotype represents Usher syndrome type 1C and is explained by the USH1C defect." (PMID 37065762, 2023).
Usher syndrome (continued). "GRXCR1 is an enzyme that has been shown to remove glutathione groups from target proteins, and it has been suggested to destabilize the interaction between the Usher Syndrome proteins USH1C and USH1G in zebrafish." (PMID 35235570, 2022). "Variants from three known Usher syndrome genes USH2A, USH1G, and USH1C were found from the records retrieved." (PMID 34609590, 2022). "Five genes (USH2A, USH1G, USH1C, MYO7A, and PCDH15) were associated with Usher syndrome from Africa." (PMID 34609590, 2022). "Consistent with this, USH1C knockout mice, which were developed to model Type 1 Usher syndrome, display significant perturbations in intestinal brush border morphology." (PMID 33815460, 2021). "Currently, up to 13 genes have been associated with Usher syndrome: MYO7A, USH1C, CDH23, PCDH15, USH1G, and CIB2 are responsible for USH1, although the role of CIB2 in the Usher syndrome has recently been put on doubt." (PMID 31231422, 2019). "In this study, we have identified a critical time at which treatment must occur in order to rescue IHC and OHC function in a mouse model of Usher syndrome using ASOs that correct Ush1c c.216A gene expression." (PMID 29027038, 2018). "The structural variants observed using this approach were identified in genes as diverse as the conditions themselves involving gyrate atrophy (OAT), retinitis pigmentosa (USH2A) and Usher syndrome (USH1C)." (PMID 29099798, 2017). "The “rarest” Usher syndrome genes with mutations were as follows: USH1G (1 patient), CLRN1 (1 patient), PCDH15 (2 patients), and USH1C (4x)." (PMID 28944237, 2017). "In LER (CD−M2), Ush1c, Otogl, Gjb2, and Eps8 were associated with NSHL; Ush1c and Clrn1 with Usher syndrome, Six1 with branchiootorenal syndrome; Gjb2 with skin phenotype and HL; Gata3 with hypoparathyroidism, sensorineural hearing loss, and renal dysplasia; and Col9a2 with Stickler syndrome." (PMID 39684410, 2024). "Furthermore, elucidation of the three distinct forms of Usher Syndrome Type 1 demonstrated that USH1B, USH1C, and USH1D are distinct genetic disorders caused by mutations in three different genes, MYO7A, CHD23, and USH1C, respectively." (PMID 33671976, 2021). "USH1G interacts with USH1C, a known gene involved in Usher syndrome." (PMID 30828346, 2019). "A gene therapy approach whereby preparations of an antisense oligonucleotide to correct defective USH1C protein was successfully applied to cochleas in knockout mice generated to have symptoms similar to Usher syndrome, another hereditary child deafness syndrome." (PMID 23967136, 2013). "Usher syndrome is heterogenous, both in terms of clinical presentation and genetic origin, with a number of diverse genes known to carry pathogenic mutations (Type 1: MYO7A, USH1C, PCDH15, CDH23, USH1G, and CIB2; Type 2: USH2A, ADGRV1, and WHRN; Type 3: CLRN1)." (PMID 38474133, 2024). "Notably, Müller glial cells also expressed the other USH1-associated genes USH1G, USH1C, CDH23, and CIB2, suggesting that Müller glial cells may be more mechanistically relevant to Usher syndrome pathology than previously considered." (PMID 38474133, 2024). "The fly orthologue candidates of Usher syndrome genes MYO7A (crinkled in fly), WHRN (dyschonic in fly), USH1C (CG5921 in fly), and PCDH15 (Cad99C in fly) were localized or expressed in the actin-rich scolopale cells, consistent with our previous findings." (PMID 38412189, 2024). "In two (not knowingly related) Saudi patients with Usher syndrome and hyperinsulinism (P96 and P97), we identified a homozygous deletion of the largest part of the USH1C gene (exons 3–27)." (PMID 28944237, 2017). "However, we performed a linkage analysis for all known loci so far implicated in the Usher syndrome (data not shown), and we were able to discard linkage to all of them except for USH1B and USH1C." (PMID 21203349, 2010).
Usher syndrome (continued). "In particular, three genes implicated in Type 1 Usher syndrome (CDH23, MYO7A and USH1C), while selected for the resequencing arrays, were not incorporated in the HHL APEX array; a separate APEX array for this group of disorders was already available when the HHL APEX array was originally designed." (PMID 20668687, 2010). "Thus, there is no indication that USH1C is involved in digenic Usher syndrome, at least probably not in combination with the other USH genes found to be mutated here." (PMID 17407589, 2007).
deafness (23 papers, 2007 to 2025). An inherited or acquired condition characterized by the complete loss of the ability to hear from one or both ears. "Mutations in USH1C affect both the auditory and visual systems, causing profound bilateral deafness, vestibular dysfunction, and progressive retinitis pigmentosa." (PMID 38826689, 2024). "Among deafness genes, three variants have been identified on the USH1C gene: a nonsense variation (rs377145777), a missense variant (rs1064074), and a splice site variation with unknown impact on protein." (PMID 34440441, 2021). "The homozygous Ush1c KO mice exhibit characteristic USH1C phenotypes, including deafness and balance impairments, providing an excellent model for testing therapeutic approaches." (PMID 39871419, 2025). "Of them, 9 deafness genes expressed more in the apical turn (Pou4f3, Slc17a8, Tmc1, Crym, Otof, Ush1c, Pcdh15, Slc26a5, and Lhfpl5) and six were internal controls (Gapdh, Actb, Rps17, Rpl30, Atp6, and Ipo8)." (PMID 24676347, 2014). "In the Western Romanian population studied, the risk of deafness is given by pathogenic variants in 7 genes included in the panel: GJB2, USH2A, LOXHD1, SLC26A4, USH1C, COL4A4, COL4A3, present in almost 10% of the cohort, therefore representing a significant risk." (PMID 41303398, 2025). "They found that numerous deafness-related genes (e.g. Col9a2, Lmx1a, and Sox10) were downregulated, and single-cell transcriptome data from Chd7KO/+ organoids also showed that some deafness-related genes (e.g. Six1, Ush1c, and Strc) were downregulated in HCs, implying that." (PMID 38015350, 2024). "Interestingly, incorporation of faulty amino acids, as caused by missense mutations in USH1C, results only in isolated deafness but not in retinal degeneration." (PMID 23027640, 2012). "It is notable that the paralogs PDZD7, USH1C, and DFNB31 are all deafness genes and interact with MYO7A." (PMID 27525485, 2016). "In addition, mutations in MYO7A, USH1C, DFNB31, CIB2, CDH23 and PCDH15 were also reported in non-syndromic deafness without retinal degeneration and mutations in USH2A and CLRN1 have been reported in patients with isolated RP or retinal dystrophies and no deafness." (PMID 25211151, 2014).
hearing loss (16 papers, 2012 to 2024). "While difficult to put a number on the minimal number of transcripts needed, studies on splice modulation therapy for USH1C-associated hearing loss indicate that 20% of functional USH1C transcripts is sufficient for inner ear function." (PMID 33815940, 2021). "Mutations in USH1C exons B and D underlie DFNB18, a non-syndromic hearing loss disorder." (PMID 36936679, 2023). "The results of gene expression analysis of each cochlear turn showed that 4 ADNSHL genes (Pou4f3, Slc17a8, Tmc1, and Crym) and 9 autosomal recessive non syndromic hearing loss genes (Otof, Strc, Ush1c, Pcdh15, Grxcr1, Dfnb59, Slc26a5, Lhfpl5, and Ptprq) were changed 2-fold or more." (PMID 24676347, 2014). "Mutations of MYO7A, CDH23, USH1C, PCDH15, USH1G, and WHRN can cause non-syndromic recessive hearing impairment, and MYO7A variants are also associated with a non-syndromic dominant form of hearing impairment." (PMID 35353227, 2022). "The variants in DIAPH3 and USH1C were investigated in the pedigree by Sanger sequencing, and their segregation was not compatible with the segregation of hearing loss in the family." (PMID 33326993, 2021). "USH1C therefore should be considered a candidate gene in patients with USH1, nonsyndromic hearing loss, young (<40 years) RP patients with normal hearing function, and RP patients with mild or late-onset hearing loss." (PMID 23251578, 2012). "Variants in MYO7A, USH1C, CDH23, PCDH15, and WHRN are also responsible for non-syndromic hearing loss associated with loci DFNB2 and DFNA11, DFNB18, DFNB12, DFNB23, and DFNB31, respectively." (PMID 38525684, 2024).
retinal degeneration (5 papers, 2012 to 2025). Degeneration of the retina. "Considering the late onset of the retinal degeneration in USH1 we do not expect the regulation of the cWnt signaling by USH1C/harmonin to play a role during retinal development." (PMID 36846582, 2023).
retinitis pigmentosa (5 papers, 2017 to 2025). Retinitis pigmentosa (RP) is an inherited retinal dystrophy leading to progressive loss of the photoreceptors and retinal pigment epithelium and resulting in blindness usually after several decades. "The rp2, cerkl, myo7aa, ush1c and pcdh15a genes are related to retinitis pigmentosa." (PMID 38789412, 2024).
autoimmune enteropathies (2 papers, 2012 to 2023). "Before designated as a gene causative of USH1C, the USH1C gene product harmonin was first identified as an autoimmune antigen, synonymously named PDZ-73 and AIE-75, being upregulated in colorectal carcinomas and in cases of autoimmune enteropathy (AIE)." (PMID 36846582, 2023).
Bardet–Biedl syndrome 19 (1 paper, 2024). "While pathogenic variants in USH1C and IFT27 are associated with autosomal recessive Usher syndrome type 1C and Bardet–Biedl syndrome 19, respectively, mutated ADGRA3 is linked to autosomal recessive RP." (PMID 39766861, 2024).
colorectal cancer (1 paper, 2023). A primary or metastatic malignant neoplasm that affects the colon or rectum. "Interestingly, only the retina and inner ear show a disease-related phenotype, although USH1C/harmonin is almost ubiquitously expressed in the human body and upregulated in colorectal cancer." (PMID 36846582, 2023).
cancer (3 papers, 2021 to 2023). A tumor composed of atypical neoplastic, often pleomorphic cells that invade other tissues. "We combine a highly sensitive CTC capture assay exploiting the cancer cell binding recombinant malaria VAR2CSA protein (rVAR2) with the detection of colon-related mRNA transcripts (USH1C and CKMT1A)." (PMID 34884994, 2021). "The mRNA expression level of FXYD3, LGALS4, USH1C, ECI2, TGM2, and HMGA2 genes which are involved in EMT, drug resistance, and cancer progression were measured in HCT116/OX-R4.3 and HCT116/OX-R10 cells by qRT-PCR." (PMID 37535601, 2023).
genetic disorders (3 papers, 2021 to 2025). "Our approach, which demonstrates long‐lasting gene expression in the Ush1c KO mouse model, suggests that similar strategies could enhance gene therapies for a range of genetic disorders, ultimately providing substantial benefits to affected patients." (PMID 39871419, 2025).
tumor (3 papers, 2017 to 2024). "Transcriptomic profile analysis showed that two genes (L1CAM and FBN1) were upregulated and that four genes (AUST2, MAPT, AGT and USH1C) and two microRNAs (hsa-mir-100 and hsa-mir-378) were downregulated, all of which were associated with tumor malignancy." (PMID 29215599, 2017). "With regards to the clinical analysis of ccRCC samples from microarrays of GSE66272 and GSE73731, the upregulation of L1CAM and FBN1 and downregulation of AUTS2, MAPT, AGT and USH1C were observed along with an increase in tumor grade." (PMID 29215599, 2017). "However, the USH1C gene showed tumor-specific expression compared with that of the levels of nontumor tissues in TCGA-KIRC data (p = 6.0 × 10−9) and GSE105288 (p = 0.503)." (PMID 35625960, 2022). "We found that the expression levels of two upregulated genes (L1CAM and FBN1) were also increased along with tumor grade and that the expression levels of four downregulated genes (AUTS2, MAPT, AGT and USH1C) were decreased along with tumor grade." (PMID 29215599, 2017).
USH1C also shares sentences with these, for which no sentence is quoted: Usher syndrome type 1C (15 papers); Blindness (4); enteropathy (2); hyperinsulinism (2); renal carcinoma (2); autosomal recessive retinitis pigmentosa (1); CHARGE syndrome (1); Cirrhosis (1); colon cancer (1); DOORS syndrome (1); enterocolitis (1); gyrate atrophy (1); Hearing (1); Hearing impairment (1); hypoparathyroidism (1); microtia (1); renal dysplasia (1); retinal ciliopathy (1); sensorineural hearing loss (1); Stickler syndrome (1); Wolfram syndrome (1).